TCHHL1 (trichohyalin like 1)
Synonyms: S100A17; THHL1
Tractability: No criterion of Open Targets' tractability assessment is met for any kind of drug.
Gene: Protein-coding gene on chromosome 1 (152,084,141 to 152,089,064, reverse strand). Ensembl gene ENSG00000182898.
Subcellular location (Human Protein Atlas): Nuclear membrane; Nucleoli
Gene Ontology:
Molecular function: transition metal ion binding
Genetic constraint (gnomAD): Loss-of-function variants: 5 observed, 6.08 expected, observed/expected ratio (o/e) 0.82, 90% interval 0.43 to 1.64. That is too few expected variants to judge how well the gene tolerates losing a copy. Missense variants: 1,027 observed, 1,084.8 expected, observed/expected ratio (o/e) 0.95, 90% interval 0.9 to 1. Synonymous variants: 405 observed, 397.26 expected, observed/expected ratio (o/e) 1.02, 90% interval 0.94 to 1.11.
Homologues: Orthologues: chimpanzee TCHHL1 (98% identical), macaque TCHHL1 (84% identical), dog TCHHL1 (59% identical), pig TCHHL1 (59% identical), rabbit TCHHL1 (53% identical), mouse Tchhl1 (35% identical), rat Tchhl1 (31% identical), Drosophila melanogaster Cp190 (12% identical), Drosophila melanogaster CG12592 (9% identical), Drosophila melanogaster CG9915 (6% identical), Caenorhabditis elegans F13B12.1 (5% identical). Paralogues in human: MDN1 (25% identical), IWS1 (10% identical), SAMD15 (9% identical).
Diseases named in the same sentence as TCHHL1 in open-access papers:
TCHHL1 is named in the same sentence as 9 diseases in open-access papers, as found by Europe PMC text mining. Sharing a sentence is not in itself a finding about the gene and the disease. The quoted sentences say what the papers report.
asthma (1 paper, 2020). "The exceptions were four variants located on chromosomes 1q21.3 (in/near TCHHL1, HRNR, FLG and SPRR2A) which had significantly stronger effects on age-of-onset of eczema, and one on 17q12 (in GSDMB) which had a stronger effect on the age-of-onset of asthma." (PMID 32603359, 2020).
cervical cancer (1 paper, 2021). A primary or metastatic malignant neoplasm involving the cervix. "Although the relationship between TCHHL1 and cervical cancer remains unclear, the high expression of TCHHL1 plays an important role in promoting the proliferation of squamous cells." (PMID 34030694, 2021).
eczema (1 paper, 2020). "Four of these had a stronger effect on the age-of-onset of eczema: those in/near HRNR (rs1213821), FLG (rs61816761), TCHHL1 (rs115045402), SPRR2A (rs184587444), all within a 1 Mb locus on chromosome 1q21." (PMID 32603359, 2020).
squamous cell carcinoma (1 paper, 2020). A carcinoma arising from squamous epithelial cells. "We herein examined the role of TCHHL1 in normal human keratinocytes (NHKs) and squamous cell carcinoma (SCC)." (PMID 33133644, 2020).
tumor (3 papers, 2014 to 2023). "In contrast, in well-differentiated SCCs, the signals of TCHHL1 were observed to be stronger in the peripheral areas than in the center areas of the tumor nests." (PMID 33133644, 2020). "In the poorly differentiated-SCC samples, the tumor nests were relatively small and almost all tumor cells strongly expressed TCHHL1." (PMID 33133644, 2020). "As S100A5, S100A7, S100A7A, S100Z, TCHHL1, and S100G are ubiquitously expressed at low levels in both tumor and paratumor samples, they were not included in the following analyses." (PMID 37133437, 2023).
TCHHL1 also shares sentences with these, for which no sentence is quoted: bladder cancer (1 paper); cancer (1); infection (1); skin disorder (1).